PMIS2 (PMIS2 transmembrane protein)
Description:
May play a role in spermatozoa mobility.
Synonyms: IFITMD9
Gene: Protein-coding gene on chromosome 19 (35,586,161 to 35,587,296, forward strand). Ensembl gene ENSG00000283758.
Subcellular location: Membrane
Gene Ontology:
Cellular component: membrane
Homologues: Orthologues: rabbit PMIS2 (53% identical), mouse Pmis2 (31% identical), zebrafish tmem91 (17% identical). Paralogues in human: SYNDIG1L (25% identical), SYNDIG1 (23% identical), TMEM91 (17% identical).